TAS2R14 (taste 2 receptor member 14)
Description:
Gustducin-linked G protein-coupled receptor that plays a role in the perception of bitterness. The activity of this receptor stimulates GNAT3, activating the gustducin G protein pathway. Likely plays a role in sensing the chemical composition of the gastrointestinal content and other extra-oral tissues via the inhibitory G protein pathways.
Synonyms: T2R14; TRB1; PRH1-TAS2R14
Tractability: Small molecule: a structure with a bound ligand is known; a high-quality ligand is known. Antibody: its Gene Ontology location is reachable by antibodies, with high confidence; UniProt predicts a signal peptide or a membrane-spanning region. PROTAC: a small molecule that binds it is known.
Target class: Membrane receptor; Taste receptor (taste family GPCR); Taste family G protein-coupled receptor
Gene: Protein-coding gene on chromosome 12 (10,937,408 to 11,171,573, reverse strand). Ensembl gene ENSG00000212127.
Subcellular location: Membrane
Pathways (Reactome):
Signal Transduction: Class C/3 (Metabotropic glutamate/pheromone receptors); G alpha (i) signalling events
Sensory Perception: Sensory perception of sweet, bitter, and umami (glutamate) taste
Gene Ontology:
Molecular function: bitter taste receptor activity; taste receptor activity; G protein-coupled receptor activity
Biological process: detection of chemical stimulus involved in sensory perception of bitter taste; G protein-coupled receptor signaling pathway; sensory perception of taste
Cellular component: membrane; plasma membrane
Genetic constraint (gnomAD): Loss-of-function variants: 0 observed, 0.16 expected, observed/expected ratio (o/e) 0, 90% interval 0 to 1.88. That is too few expected variants to judge how well the gene tolerates losing a copy. Missense variants: 376 observed, 384.25 expected, observed/expected ratio (o/e) 0.98, 90% interval 0.9 to 1.07. Synonymous variants: 130 observed, 135.73 expected, observed/expected ratio (o/e) 0.96, 90% interval 0.83 to 1.11.
Homologues: Orthologues: chimpanzee TAS2R14 (99% identical), macaque TAS2R14 (84% identical), rat Tas2r116 (49% identical), mouse Tas2r125 (49% identical), rat Tas2r125 (49% identical), mouse Tas2r116 (49% identical), rat Tas2r117 (49% identical), rat Tas2r140 (49% identical), mouse Tas2r140 (48% identical), mouse Tas2r103 (47% identical), mouse Tas2r113 (47% identical), mouse Tas2r110 (47% identical), and 10 more. Paralogues in human: TAS2R13 (46% identical), TAS2R31 (44% identical), TAS2R30 (44% identical), TAS2R43 (44% identical), TAS2R46 (43% identical), TAS2R19 (42% identical), TAS2R50 (42% identical), TAS2R20 (41% identical), TAS2R7 (37% identical), TAS2R10 (36% identical), TAS2R42 (34% identical), TAS2R3 (32% identical), and 11 more.
Diseases named in the same sentence as TAS2R14 in open-access papers:
TAS2R14 is named in the same sentence as 33 diseases in open-access papers, as found by Europe PMC text mining. Sharing a sentence is not in itself a finding about the gene and the disease. The quoted sentences say what the papers report.
breast carcinoma (6 papers, 2020 to 2024). "The activation of TAS2R4 and TAS2R14 by quinine or apigenin led to a significant concentration-dependent reduction in cell proliferation of the breast cancer cell line MDA-MB-231, while proliferation of MCF-10A, the normal breast epithelial cells, was only attenuated at higher ligand concentrations." (PMID 34885005, 2021). "Singh and colleagues found significant differences in the expression levels of TAS2Rs in different types of breast cancer cell lines, such as decreased mRNA expression levels of TAS2R4 and increased mRNA expression levels of TAS2R14." (PMID 38999959, 2024). "The TAS2Rs with highest expression in HNSCC (TAS2R4, TAS2R14, TAS2R19, TAS2R20, TAS2R30, TAS2R43, and TAS2R45) overlap with TAS2Rs expressed at increased levels in breast cancer." (PMID 34717036, 2022). "In contrast, the expression level of TAS2R14 in breast cancer cell lines is higher than in the noncancerous control group, suggesting that TAS2R14 may have different mechanisms of action in breast cancer development." (PMID 38999959, 2024).
colorectal cancer (4 papers, 2010 to 2023). A primary or metastatic malignant neoplasm that affects the colon or rectum. "We conducted a study to investigate the hypothesis that genetic variants of TAS2R14 could influence its ability to bind bitter toxic compound, initiate the elimination of xenobiotic and thus increase the risk of colorectal cancer." (PMID 20534144, 2010). "Since bitter taste sensitivity has been reported to be associated with smoking and alcohol consumption, we explored at the same time the association of TAS2R14 common variants with anthropometric measures, behavioural traits like smoking and alcohol consumption and colorectal cancer susceptibility." (PMID 20534144, 2010). "Furthermore, activation of TAS2R14 in a human colorectal cancer cell line is supposed to result in increased GDF15 levels, which is involved in several biological functions like anti-inflammatory and apoptotic pathways." (PMID 37286811, 2023). "Previous studies already showed that the bitter-tasting compounds diclofenac (TAS2R14) and resveratrol (TAS2R14, TAS2R39) increased the NSAID-activated gene (NAG-1), which was later renamed GDF15, in a human colorectal carcinoma cell line." (PMID 34784295, 2022).
asthma (3 papers, 2021 to 2024). "In the later stage, the main components of ACH and BCH will be studied from the level of cells, how to regulate TRPV1 and TAS2R14 to improve calcium homeostasis, and regulation to improve the asthma rat model was further verified." (PMID 36045655, 2022). "In this study, the mechanisms of ACH, BCH, and their combination (SGMHD) on asthma inflammation and regulation of TRPV1 and TAS2R14 were discussed from the level of animal experiments." (PMID 36045655, 2022). "We also verified that FFA mediated relaxation of ASMCs by activating TAS2R14 signaling pathway and opening BKCa channels, and the efficacy of FFA was similar to that of conventional β-agonist to relax ASMCs and abrogate airway resistance in animal models of asthma." (PMID 38389834, 2024).
colon cancer (2 papers, 2010 to 2024). "Utilizing univariate Cox regression analysis, we identified seven TAS2Rs genes associated with prognosis in colon cancer patients, including TAS2R4, TAS2R5, TAS2R14, TAS2R19, TAS2R20, TAS2R31, and TAS2R38." (PMID 38999959, 2024). "Our results show that compared to normal colon tissue, the expression levels of multiple bitter taste receptor genes are elevated in colon cancer tissue, including TAS2R4, TAS2R5, TAS2R14, TAS2R19, TAS2R20, TAS2R31, and TAS2R38." (PMID 38999959, 2024). "Differential expression analysis results revealed that compared to normal colon tissue, colon cancer samples exhibited elevated expression levels of TAS2R1, TAS2R4, TAS2R5, TAS2R14, TAS2R19, TAS2R20, and TAS2R38 (p < 0.05), with the exception of TAS2R60, which was downregulated." (PMID 38999959, 2024).
epithelial ovarian cancer (2 papers, 2021). "In the epithelial ovarian cancer cell line SKOV3, exposure to noscapine, a TAS2R14 agonist, led to increased pro-apoptotic and decreased pro-survival protein expression." (PMID 34885005, 2021).
adrenocortical carcinoma (1 paper, 2022). "Increased TAS2R14 expression was associated with worse survival in adrenocortical carcinoma (−1757 days, p < 0.001) and esophageal adenocarcinoma (−640 days, p = 0.0041), but improved survival in non-papillary bladder cancer (+ 343 days, p = 0.0436)." (PMID 35624283, 2022). "The area under the receiver operating characteristics was highest for TAS2R14 in adrenocortical cancer with associated sensitivity 65.4% and specificity 71.7%." (PMID 35624283, 2022). "Adrenocortical carcinoma had the largest negative survival association for TAS2R14 with mean survival difference of −1757 days (p = 0.0007)." (PMID 35624283, 2022). "The most notable survival associations were seen for expression of TAS2R14 in adrenocortical carcinoma, esophageal adenocarcinoma, and non-papillary bladder cancer which were significant based on analysis of mean survival difference and Kaplan–Meier analysis." (PMID 35624283, 2022). "Kaplan–Meier survival analyses for high- and low-expression groups of TAS2R14 were statistically significantly associated with survival for adrenocortical cancer (p = 0.0011), non-papillary bladder cancer (p = 0.0025), and esophageal adenocarcinoma (p = 0.026)." (PMID 35624283, 2022).
allergic asthma (1 paper, 2017). A asthma with a basis in a pathological type I hypersensitivity reaction. "Moreover, direct TAS2R14 agonists such as noscapine can inhibit IgE-dependent mast cell activation, which was thought to be a promising approach to allergic asthma treatment." (PMID 28939897, 2017). "Thus, this study was devoted to identifying direct TAS2R14 agonists from Radix Bupleuri and evaluating their efficacy in inhibiting mast cell degranulation, which is an important mechanism in allergic asthma." (PMID 28939897, 2017).
melanoma (1 paper, 2022). A malignant, usually aggressive tumor composed of atypical, neoplastic melanocytes. "The most dramatic positive survival association was present in melanoma distant metastases for TAS2R14 with the high-expression group surviving a mean 2641 days (~ 7.2 years) longer than the low-expression group (p = 0.0127)." (PMID 35624283, 2022).
obstructive lung disease (1 paper, 2021). "This has brought forth the concept that TAS2R14 agonists might be useful for treating obstructive lung disease where HASM contraction plays an active role in airway obstruction." (PMID 33465377, 2021).
prostate carcinoma (1 paper, 2021). A carcinoma that arises from epithelial cells of the prostate gland. "Similarly, the activation of TAS2R14 reduced cell survival in prostate cancer cell lines too." (PMID 34885005, 2021).
cancer (8 papers, 2017 to 2026). A tumor composed of atypical neoplastic, often pleomorphic cells that invade other tissues. "The G-protein-coupled receptor taste receptor type 2 member 14 (T2R14 or TAS2R14) is expressed in various cancer types." (PMID 41677642, 2026). "Cucurbitacin B, a triterpenoid known to act as an agonist for TAS2R10 and TAS2R14, shows promising anti-inflammatory and anti-cancer actions specific to the skin." (PMID 38248322, 2023). "The RT-qPCR analysis showed that TAS2R14 was downregulated in most cancer cell lines and cancer tissue." (PMID 34885005, 2021). "Agonists of TAS2R14, including quercetin and naringenin, have exhibited anti-cancer activities in various cancer types, including NB cells." (PMID 28467517, 2017). "Similarly, noscapine exhibited anti-cancer actions through TAS2R14 in epithelial ovarian and prostate tumor cells, impacting cell survival." (PMID 38248322, 2023).
tumor (4 papers, 2019 to 2026). "Changes in expression for TAS1R1, TAS1R3, TAS2R4, TAS2R5, TAS2R14, TAS2R19, and TAS2R20 had survival associations in at least one tumor histology." (PMID 35624283, 2022). "Some GPCRs have low median expression (<1 TPM) in the tumor population in general (e.g., taste receptors TAS2R14 and TAS2R20 in ESCA) but may be expressed in subsets of these populations, wherein they may contribute to differences in survival." (PMID 31765370, 2019).
infection (3 papers, 2021 to 2025). The state of being infected such as from the introduction of a foreign agent such as serum, vaccine, antigenic substance or organism. "Additionally, rs3851584 in TAS2R14 showed a borderline significant association with the infection (p = 0.058)." (PMID 41153757, 2025). "First, the mechanistic link between TAS2R14 and bacterial sensing remains unclear—does S. aureus directly activate TAS2R14 via secreted metabolites, or is the receptor responding to host‐derived signals during infection?" (PMID 40709685, 2025).
respiratory disease (2 papers, 2017 to 2025). "Consequently, determining direct TAS2R14 agonists could be valuable for treating respiratory diseases and exploring their biological mechanisms." (PMID 28939897, 2017). "Thus, TAS2R14 has great potential as a therapeutic target against respiratory diseases." (PMID 28939897, 2017).
TAS2R14 also shares sentences with these, for which no sentence is quoted: COVID-19 (2 papers); oral cancer (2); acute myeloid leukaemia (1); bacterial infection (1); chronic obstructive pulmonary disease (1); cystic fibrosis (1); esophageal adenocarcinoma (1); inflammation (1); kidney clear cell carcinoma (1); metabolic disease (1); metabolic syndrome (1); morbid obesity (1); nonalcoholic fatty liver disease (1); Obesity (1); ovarian cancer (1); pancreatic cancer (1); polyp (1); upper respiratory infections (1); viral infections (1).